APOE (apolipoprotein E)
Diseases named in the same sentence as APOE in open-access papers (continued):
Sharing a sentence is not in itself a finding about the gene and the disease.
melanoma (continued). "In melanoma, LXR agonists robustly suppressed melanoma progression through the transcriptional induction of APOE." (PMID 37310025, 2023). "TREM2+ TAMs from ESCC exhibited a consistent expression pattern and identical signature genes (TREM2, SPP1, APOE, C1QC, C1QB, and C1QA) with melanoma cells, suggesting that TREM2+ TAMs were associated with immunotherapy resistance in ESCC." (PMID 37187751, 2023). "As previously shown, MNT1 cells express ApoE, an inhibitor of melanoma progression, and secrete ApoE through sEVs." (PMID 36835115, 2023). "APOE is secreted by melanoma cells and targets the low density lipoprotein receptor-related protein 1 (LRP1) receptor on other melanoma cells and the LRP8 receptor on endothelial cells, leading to the inhibition of migration of melanoma cells." (PMID 35884446, 2022). "The cancer-secreted LRP1 ligand, Apolipoprotein E (ApoE), suppresses invasion and metastatic melanoma cells through LRP1." (PMID 36612285, 2022). "The conditioned media from wild type ApoE secreting melanoma cells suppress T-cell activation in vitro while this suppressive effect is absent in conditioned media from ApoE knock out tumor cells." (PMID 36341364, 2022). "MDSC blockade by LXR-induced ApoE enhanced cytotoxic T cell activation in B16-F10 bearing mice and patients, eventually leading to reduced melanoma growth." (PMID 36341364, 2022). "We identify tumor secreted apoE as a novel checkpoint enabling immune evasion in a mouse melanoma tumor model." (PMID 36341364, 2022). "In contrast, it is reported that apoE is involved in the inhibition of melanoma metastases and has anti-angiogenic properties." (PMID 36341364, 2022). "We investigated the expression of apoE in mouse melanoma and the role of apoE in the context of tumor growth and immunity." (PMID 36341364, 2022). "To evaluate the systemic levels secreted from the mouse melanoma tumor itself, we measured the level of serum apoE in apoE KO (apoE−/−) C57/BL6 mice inoculated subcutaneously (s.c.)with 104 WT B16 (F10) cells injected in the right thigh." (PMID 36341364, 2022). "Previous studies have shown that the liver-X nuclear receptor (LXR)/ApoE axis reduce MDSC abundance in murine melanoma models by binding to Lrp8 receptor on MDSC." (PMID 36341364, 2022). "In melanoma, miR-1908, miR-199a-5p, and miR-199a-3p can target apolipoprotein E (ApoE) synergistically to augment metastatic invasion and colonization." (PMID 36302748, 2022). "Together, the multiple experiments presented, establish the potent inhibitory effects of apoE on immune cell function and activation of immune signaling in the melanoma mouse model." (PMID 36341364, 2022). "To investigate the premise of ApoE being a potent immune checkpoint, we challenged WT, apoE-/- and lrp8-/- mice with WT and ApoE knock out B16-F10 melanoma tumor cells." (PMID 36341364, 2022). "We demonstrate that ApoE is -highly expressed in wild-type B16-F10 melanoma and serum levels progressively increase as tumors grow." (PMID 36341364, 2022). "Ablating ApoE in mouse melanoma enabled tumor cell rejection and induced robust immune activation and tumor immunity." (PMID 36341364, 2022). "Immuno-phenotyping of the tumor micro-environment in mice that grew tumors, revealed the highest levels of immune pathway activation and immune cell infiltrates in the apoE-/- mice that received apoE-/- B16 melanoma cells as detected by RNA transcripts." (PMID 36341364, 2022). "To understand the correlation between immunity and APOE expression in patients with melanoma, we accessed the raw RNA-seq data from the TCGA melanoma datasets (measured by RSEM algorithm) (n=462)." (PMID 36341364, 2022). "ApoE is abundantly present in B16-F10 melanoma tumors and serum levels of apoE increase dramatically with melanoma tumor growth." (PMID 36341364, 2022).
melanoma (continued). "We found ApoE to be abundantly expressed in the B16-F10 melanoma cell line and was actively secreted by these tumor cells into the serum of the host as the tumors establish and grow." (PMID 36341364, 2022). "In the current study we assess immunosuppressive modulators in the melanoma model and the modulator that was most highly expressed by qPCR in the B16-F10 melanoma is ApoE." (PMID 36341364, 2022). "According to the analysis of human melanoma scRNA-seq, myeloid cells associated with responders showed a relatively high expression of PLTP, APOC1, APOE, MT1G, and MT1H." (PMID 34966676, 2021). "In order to verify the involvement of APOE and of cholesterol metabolites in metastatic melanoma, we measured the level of oxysterols in melanoma cells." (PMID 32749065, 2020). "For instance, it has been shown that myriocin, a potent SPT inhibitor, suppresses murine melanoma growth and mediates the regression of atherosclerotic lesions in hyperlipidemic apolipoprotein E knockout mice." (PMID 31632963, 2019). "We intravenously injected an identical number of melanoma cells (B16F10) into ApoE KO and WT mice fed with normal diet (ND) or high-fat diet (HFD) and quantified metastatic lesions in the lungs after 3 weeks." (PMID 31275318, 2019). "Contradictorily, ApoE suppresses metastasis by reducing the invasive behavior of cancer cells and by inhibiting endothelial cells recruitment in melanoma." (PMID 29458390, 2018). "Nonetheless, it has been reported that miR-199a-5p induces melanoma metastasis and angiogenesis by inhibiting ApoE, an inhibitor of metastasis and angiogenesis, through interaction at distinct ApoE receptors." (PMID 29137361, 2017). "recently published that LXRβ activation not only within the tumor cells, but also in stromal cells, induces the production of apolipoprotein E (ApoE) that suppresses melanoma invasion, angiogenesis, tumor progression, and metastasis." (PMID 27308405, 2015). "Similarly, mice bearing the human APOE ε4 variant show enhanced anti-tumor immune activation and reduced melanoma progression compared to those with APOE ε2." (PMID 40149482, 2025). "It seems ApoE can suppress the progression of melanoma and influence the metastatic cascade." (PMID 40662483, 2025). "Barcode group 2 uniquely expressed lipid metabolism genes, such as FASN and APOE, which contribute to melanoma resistance by promoting MAPK inhibitor resistance through reducing lipid poly-unsaturation and protecting MITF^low/AXLĥigh persister cells from ferroptosis, respectively." (PMID 41000875, 2025). "Even though the high expression of APOE was shown to promote tumor development, proliferation, and metastasis, previous studies demonstrated that in some cancers, such as ovarian cancer and melanoma, the high expression of APOE shows protective effects, which is consistent with our results." (PMID 37434484, 2023). "ApoE is a novel checkpoint with extensive and potent suppressant effects in mouse melanoma." (PMID 36341364, 2022). "We investigated the role of apoE in the immune micro-environment using a mouse melanoma model." (PMID 36341364, 2022). "In summary, apoE plays a broad role in immune resistance observed in the WT B16 melanoma tumors." (PMID 36341364, 2022). "Interestingly, higher ApoE protein levels appear to have a suppressive effect on melanoma invasion and metastasis." (PMID 35892323, 2022). "The potent immune-suppressive effects of ApoE in the melanoma mouse model suggests that APOE may be an important regulator of immunity in human melanoma." (PMID 36341364, 2022). "Importantly, these data were confirmed also in the other cohort of melanoma cells, where 24‐hydroxycholesterol showed the best correlation with APOE levels, indicating a specific cholesterol metabolism activation in metastatic melanoma." (PMID 32749065, 2020).
melanoma (continued). "In a panel of 60 diverse human cancer cell lines (NCI-60) used by the Developmental Therapeutics Program of the US National Cancer Institute, we also found that both APOA1 and APOE mRNA levels were low, with the exception, for apoE only, of the T-47D cell line and melanoma cell lines." (PMID 32321558, 2020). "Moreover, melanoma is also characterized by higher mRNA levels of APOE and PMEL with respect to healthy donors (Fig EV3G)." (PMID 32749065, 2020). "However, it was also reported that ApoE is involved in the inhibition of melanoma metastasis and angiogenesis." (PMID 31275318, 2019). "Using co-culture of B16F10 mouse melanoma cells and spleen-derived NK cells from WT or ApoE mice, we found that NK cells derived ApoE mice (ApoE KO NK cells) showed more significantly increased cytotoxicity compared to NK cells derived from WT mice (WT NK cells)." (PMID 31275318, 2019). "Using wound scratch assay and trans-well migration assay, we determined whether ApoE expression affects B16F10 melanoma migration." (PMID 31275318, 2019). "In addition, the striking finding of this study is that the prognostic impact of different apoE subtypes on HCC is opposite to that in melanoma, emphasizing the variability and complexity in the mechanisms of tumour immune escape among different cancer species and organ backgrounds." (PMID 38976030, 2024). "However, it was also clarified that LRP1 may play a role as a suppressor receptor for the metastatic phenotype in melanoma in response to ApoE." (PMID 36839884, 2023). "The effect of apoE seems to be at least partially mediated by its interaction with the Lrp8 receptor as this group also had slower tumor growth and rejection of tumor cells when apoE-/- melanoma cells were inoculated into Lrp8-/- mice, endorsing the in vitro findings in splenocyte studies." (PMID 36341364, 2022). "Thus, the results described for ApoE secreted from B16 melanoma tumor cells may impair activation of pro-inflammatory DCs and can be interpreted in an opposite direction." (PMID 36341364, 2022). "As expected, TREM2+ TAMs from ESCC specifically expressed TREM2, SPP1, APOE, and three complement genes, consistent with TREM2+ TAMs from melanomas." (PMID 37187751, 2023). "Among them, DNAJA4 can positively regulate ApoE, and extracellular ApoE can target the LRP1 receptor of melanoma cells and the LRP8 receptor of endothelial cells, thereby inhibiting cancer cell invasion, metastasis, colonization, and endothelial recruitment." (PMID 35463352, 2022). "Thus, reduced growth rate and increased immunogenicity of ApoE-/- B16 melanoma cells in vivo could be more dependent on Cas9 than ApoE-deficiency, however several of our B16-F10 melanoma controls do have CRISPR/Cas9 expression alone that do not seem to alter immunogenicity." (PMID 36341364, 2022). "In melanoma, miR-1908-5p can target DNAJA4 and ApoE to promote the invasion and metastasis of MeWo-LM2 cells." (PMID 35463352, 2022). "miR-1908-5p targets APOE and DNAJA4 and promotes the invasion and metastasis of melanoma cells (MeWo-LM2)." (PMID 35463352, 2022). "Earlier studies demonstrated that ApoE and tPA binding to LRP1 drives melanoma cell proliferation and metastasis." (PMID 36612285, 2022). "The LRP1 ligand ApoE is targeted by miR-199a-3p and -5p, and miR-1908 and the heat shock factor DNAJA4, suppressing LRP1 signaling on melanoma and LRP8 on endothelial cells." (PMID 36612285, 2022). "In murine models of melanoma, ApoE secreted by melanoma cancer cells suppressed tumor invasion and metastatic endothelial cell recruitment by binding to LRP1-positive melanoma cells and LRP8-positive endothelial cells." (PMID 33669052, 2021). "It is known that high levels of MITF, APOE, and SPP1 mark different aspects of melanoma progression, i.e., melanocyte differentiation, angiogenesis, and inflammation, respectively." (PMID 33202765, 2020).
melanoma (continued). "In this study, we selected the non-tumorigenic pigmented melanoma cell line MNT-1 that expresses ApoE, a positive regulator of melanocyte pigmentation and a negative regulator of melanoma progression." (PMID 36835115, 2023). "The conditioned media from apoE-/- tumor melanoma cells alone did not suppress T-cell function like that of WT tumor cell conditioned media." (PMID 36341364, 2022). "We further demonstrated that pathway genes differentially expressed between Black and White individuals, including VEGFA, APOE, and FGFR, are expressed by mouse melanocytes and mouse melanoma cells, where their levels are directly modulated by the degree of pigmentation." (PMID 33983985, 2021). "On the other hand, LXRβ stimulation suppresses the growth, invasion and metastasis of various melanoma cell lines by activating apolipoprotein-E (ApoE) expression but affects neither cell proliferation nor viability rates." (PMID 26452260, 2015). "APOE, a protein highly expressed in the liver and central to LDL transport through the bloodstream, also shows significant gene expression in the basal layer of SGs and in melanomas, where it induces phenotype transitions of melanoma cells between states of varying invasiveness." (PMID 40289206, 2025). "Although ApoE could suppress angiogenesis in melanoma, we did not observe significant differences of angiogenesis in tumor lesions from ApoE−/− and WT mice." (PMID 29458390, 2018). "We focused on macrophages and identified TREM2+ TAMs specifically expressing TREM2, SPP1, APOE, C1QC, C1QB, and C1QA, which were significantly upregulated in melanomas not responsive to ICB therapy." (PMID 37187751, 2023). "Similarly decreases of several apolipoproteins (APOB, APOE, APOM) in nonresponding patients have also been reported as prognostic markers for malignant melanoma." (PMID 38777088, 2024).
steatosis (52 papers, 2012 to 2026). Increased lipid within the cytoplasm of cells. "GPAM, PPP1R3B, and APOE have associations with steatosis and serum enzyme levels, but these loci have not been associated with histological features of NASH or cirrhosis." (PMID 34950105, 2021). "Our study underlines the importance of hepatocyte apoE in hepatic lipid metabolism, indicated by the suppression of diet-dependent inflammation and steatosis during high-fat, high-cholesterol intake by regulating VLDL assembly." (PMID 26695075, 2015). "Therefore, apoE−/− mice have been used in several studies on the mechanisms of liver damage associated with steatosis." (PMID 35906520, 2023). "The heatmap showed that the B4 cluster expressed a series of lipid-metabolism-associated genes, such as APOA1, APOA2, and APOA3, and UMAP plotting also showed that B4 cells highly expressed APOC1 and APOE, implying that the B4 cluster may be associated with steatosis in the ALC group." (PMID 36817578, 2023). "After 12 and 16 weeks of HFD feeding ApoE−/− mice developed minimal to mild steatosis and showed significantly decreased expression of Glo1 in comparison with upregulated Glo1 in ApoE−/− mice on a normal diet." (PMID 40141037, 2025). "APOE expression was positively correlated with steatosis grade, reduced in samples with an MAS ≥ 5 compared to MAS 1–4, and negatively correlated with fibrosis grade." (PMID 39201455, 2024). "Since the excessive lipid deposits lead to hepatocyte damage and steatosis 30, we evaluated the effects of leflunomide on lipid metabolism in livers of ApoE-/- mice." (PMID 39113703, 2024). "The cytoplasm of hepatocytes in the liver of apoE−/− mice on HFD (control) had a granular structure with signs of macrovesicular steatosis in approximately 30% of the hepatocytes." (PMID 36705799, 2024). "We found an increased expression of APOE in samples with higher steatosis grades, but it was lower along with more severe fibrosis, which is reflected in the higher APOE expression in livers with a low compared to a high MAS." (PMID 39201455, 2024). "We conclude that inhalation exposure to silica nanoparticles induced microvesicular steatosis and significantly altered the protein profile in the liver of apoE−/− mice." (PMID 35906520, 2023). "The main finding of our research is that inhaled silica nanoparticles evoked liver injury accompanied by microvesicular steatosis in the model of apoE−/− mice fed with a moderate fat content diet." (PMID 35906520, 2023). "Under special high-fat diet conditions, ApoE/NOS3−/− mice developed severe hepatocyte steatosis and hepatocyte enlargement." (PMID 36360235, 2022). "In a separate GWAS performed on the same cohort (n=14,440), four variants were associated with steatosis measured by MRI-PDFF, including APOE rs429358, a missense variant that encodes p.C112R." (PMID 34950105, 2021). "JC-5411 improved the steatosis of liver cells compared with model group by H&E staining, which is identical with the result observed in ApoE−/− mice." (PMID 33442380, 2020). "We evaluated the phenotype of livers from ApoE KO and DKO mice to determine the influence of Ron on the onset and progression of NASH-associated steatosis." (PMID 32796650, 2020). "Histopathological evaluation in ApoE–/–HFD + APH-fed mice revealed grade 1 steatosis (5–33%), which was mainly represented by micro-vesicular steatosis with a significant attenuation of fatty liver alterations and hepatocyte injury." (PMID 33291840, 2020). "On the contrary, the cytoplasm of hepatocytes in the liver of apoE−/− mice on an HFD had a granular structure with signs of macrovesicular steatosis in about 30% of cells." (PMID 30925684, 2019). "Serum lipids, liver function/steatosis, and body fat in Dagla KO, ApoE KO, and Dagla/ApoE DKO mice-fed Western diet." (PMID 26082754, 2015).